TNF (tumor necrosis factor)
Diseases named in the same sentence as TNF in open-access papers (continued):
Sharing a sentence is not in itself a finding about the gene and the disease.
viral infection (continued). "Cell sensitivity to TNF-mediated apoptosis is largely regulated by several factors including viral infections and NF-κB activation finds a critical role in regulating TNF-α sensitivity in cells by regulating the expression of several anti-apoptotic genes." (PMID 25572145, 2015). "Instead, TNFR1 is the primary transmembrane receptor for soluble TNFα, which is a mammalian cytokine released during bacterial and viral infections." (PMID 25674081, 2015). "TNF-α performs an important function in the inflammatory response and in the protection of the cells from viral infection or in promotion of selective elimination of virus-infected cells via IFN-independent mechanism." (PMID 26008237, 2015). "The data demonstrated that when cells were pretreated with SB203580, cytokines such as IL-6, IL-8, and TNF-α significantly decreased following virus infection." (PMID 26008703, 2015). "Type 1 interferons and TNF-α are types of cytokines that play an important role in the early stage of virus infection." (PMID 26098681, 2015). "For instance, expression of tumour necrosis factor (TNF)-α is enhanced in response to viral infection and it acts as a key mediator for the regression of HPV-induced lesions by exerting a cytostatic effect on normal and HPV16 immortalized keratinocytes." (PMID 25572145, 2015). "Using EBOV GP/rVSV, we next sought to assess the relative contribution of IFNγ and TNFα in inhibiting virus infection." (PMID 26562011, 2015). "We next investigated the ability of the proinflammatory cytokines TNF-α and IL-1β, rhinovirus infection, and polyinosinic-polycytidylic acid (polyI:C; as a mimic of other viral infections) to induce SOCS expression in BECs." (PMID 25630941, 2015). "Multifunctional T cells simultaneously secreting IFN-γ, TNF-α, and IL-2 play a critical role in the control of chronic bacterial and viral infections." (PMID 26339657, 2015). "The production of MIP-1 is caused by various proinflammatory factors and cytokines, such as viral infection, Gram positive bacteria, TNF-a, IFN-γ, IFN7, IL-1 α/β, IL-13 and many others." (PMID 26620310, 2015). "Although TNF-α reportedly plays an important function during virus infection, it also involved in pulmonary pathology after influenza infection." (PMID 26098681, 2015). "An epidemiological study found that children of mothers who cook with a gas stove were significantly more likely (OR = 17.1, 95% CI: 3.0-98.1) to spontaneously release TNF-α, an important indicator of an immune response to acute viral infections." (PMID 25648867, 2015). "Several lines of evidence implicate SAMHD1 in immune function, as it is upregulated in response to viral infections and is thought to play a role in mediating TNF-α proinflammatory responses." (PMID 26504826, 2015). "As expected and in light of our findings, the M(IFNγ + LPS, TNFα) signature was enriched in genes altered under intracellular parasites and bacterial, or viral infection, as well as under pro-inflammatory conditions (LPS or IFNγ)." (PMID 26302899, 2015). "Virus infection in cardiac myocytes initiated the expression of pro-inflammatory cytokines including TNF-α, IL-6, IL-1β and chemokines." (PMID 25728713, 2015). "The UK samples were not assessed for level of exposure to cigarette smoke or concurrent viral infections which we have demonstrated can significantly alter cytokine responses including TNF-α." (PMID 26284064, 2015). "In duck myotubes, HPAI H5N1 50-92 virus infection also induced a weak cytokine response, with a notable downregulation of TNF-α at 24 h p.i.." (PMID 25540384, 2015). "Increased serum levels of TNF are also detected throughout the lives of both type 1 and type 2 diabetic patients and in response to viral infection." (PMID 24466329, 2014).
viral infection (continued). "Macrophages play important roles in immune responses against various microbial and viral infections by the secretion of nitric oxide (NO) and pro-inflammatory cytokines such as tumor necrosis factor-α (TNF-α), and interleukin-6 (IL-6)." (PMID 25387351, 2014). "In order to reveal the effects of cytokines produced in response to influenza infection on virus replication, we treated moDCs with type I IFNs or proinflammatory cytokines TNF-α or IL-1β prior to H3N2 or H7N9 virus infection." (PMID 24804732, 2014). "We used a therapeutic anti-TNF-α monoclonal antibody (infliximab) to neutralize the effect of LPS-stimulated macrophages on viral infection." (PMID 24259385, 2014). "This is of great importance due to the key role that IFN-γ and TNF-α play in the protection against viral infections." (PMID 24489840, 2014). "Due to viral infection, the expression of TNF-α, IL-6, MCP-1, and IFN-β was significantly increased in cardiac fibroblasts compared to cardiomyocytes or macrophages." (PMID 25374444, 2014). "Specifically, during viral infection, TNF-α produced by cytotoxic T-cells is responsible for apoptosis and lysis of virus-infected cells." (PMID 24690491, 2014). "Pro-inflammatory cytokines, such as IL-1, IL-6, IFN-γ, and TNF-α, are among the first cytokines produced by alveolar macrophages in response to viral infections." (PMID 23631691, 2013). "Especially interferons (IFNs) and proinflammatory cytokines, such as tumor necrosis factor α (TNF-α) and interleukin IL-12 (IL-12), play a major role in controlling viral infections." (PMID 23435233, 2013). "Intestinal mast cells play a central role in innate immune response to bacterial, parasitic, and viral infections by releasing pro-inflammatory cytokines (TNF, IL-6, LTB4) that mediate neutrophil recruitment into infected tissues and bacterial clearance." (PMID 23637741, 2013). "Cytoplasmic NF-κB is activated by various stimuli, including IL-1, TNF-α and viral infection, as well as irradiation and chemotherapeutic agents." (PMID 23599797, 2013). "Following JaOArS982 virus infection, TNF-α KO mice exhibited significantly increased mortality rates when compared with WT mice." (PMID 23940775, 2013). "Tumor necrosis factor-alpha (TNF-α) is a multifunctional cytokine in the host response to inflammation, immunity, and the defense against viral infections." (PMID 23870134, 2013). "TNF-α is an important pro-inflammatory factor that plays a critical role in the formation and development of pulmonary inflammatory lesions induced by viral infection." (PMID 24039959, 2013). "This site was suggested to be responsible for the cell’s response to viral infection and TNF-α signaling." (PMID 23634222, 2013). "Viral infections are generally associated with the differentiation of IFNγ-, TNFα-, and IL-2-producing Th1 cells, driven by Type I IFN, IL-12, and IFNγ production provided by innate immune cells during viral infections." (PMID 23717308, 2013). "The serum levels of TNF-α were detectable in a minority of control subjects (2 of 10; 20%) and patients with a viral infection (6 of 26; 23%), whereas the majority of patients with a bacterial infection had detectable serum TNF-α levels (18 of 21; 85.7%)." (PMID 23690657, 2013). "During viral infection and associated TLR7/8 stimulation, macrophages produce various proinflammatory cytokines such as TNF-α and IL-6, which leads to an enhanced inflammatory response." (PMID 24191131, 2013). "Tumor necrosis factor (TNF) family cytokines are crucial in providing protection against virus infections through their regulation of cell death and survival." (PMID 23498957, 2013). "Secretion of both IFN-γ and TNF-α by effector CD8+ T cells is critically important for protection against viral infections." (PMID 23667513, 2013). "TNF-α and IL-6 are early cytokine mediators of inflammatory signaling and effectively amplify the host inflammatory response to viral infection." (PMID 23383181, 2013).
viral infection (continued). "Bacterial etiology of infection was associated with significantly (P < 0.001) elevated serum concentrations of IL-1Ra, IL-2, IL-6, and TNF-α in comparison to levels observed in the sera of patients with viral infections." (PMID 23690657, 2013). "The concentrations of IL-1Ra, IL-2, IL-6, and TNF-α were significantly higher with the sera from the patients with bacterial infections than the sera from the patients with viral infections or the controls." (PMID 23690657, 2013). "Transcriptional regulation of cardiac myokines in response to six weeks of de-training was previously demonstrated in Atlantic salmon, with down-regulation of TNFα, IL1β and IL6 being associated with higher survival in a viral disease challenge test." (PMID 23372811, 2013). "Infection with either pathogen resulted in expression of TNFα as well as IL-6, but SP induced more cytokine expression than the viral infection." (PMID 23421931, 2013). "Peak signal intensity was comparable to signal intensity of PC-3 cells treated with TNFα, a well-known activator of NFκB, as well as the signal intensity exhibited by HeLa cells following TNFα incubation or viral infection as above." (PMID 22715899, 2012). "We detected the presence of significantly higher levels of TNF-α and IL-6 in plasma samples from patients with active viral infection." (PMID 22927850, 2012). "Some of these cytokines (IL-1, IL-6, IL-17, and TNFα) are found early following virus infection and some (IL-1 and TNFα) found shortly after reactivation." (PMID 22593769, 2012). "Innate immune cytokines such as type I interferon (IFN-α/β) and tumor necrosis factor alpha (TNF-α) play fundamental roles in the early response to viral infection." (PMID 22864548, 2012). "Inasmuch as antigen presentation and cellular effector activity during a viral infection are regulated by cytokines, we evaluated the levels of serum IL-2, IL- 4, IL-6, IL-10, TNFα and IFNγ from LSIL patients and normal controls." (PMID 22642942, 2012). "The classical pathway of NF-κB activation is triggered by exposure to bacterial or viral infections and pro-inflammatory cytokines such as TNF-α." (PMID 23144891, 2012). "Both reagents also inhibited the induction of IL-6 and TNF-α mRNA expression in chorion cells after the virus infection and the secretion of IL-6 and TNF-α proteins from the cells [153, our unpublished data]." (PMID 22899878, 2012). "While both FasL and TNF-α were induced vigorously upon the viral infection, induction of TRAIL was rather mild in H1N1pdm-infected swine macrophages." (PMID 22279582, 2012). "The mean levels of TNF-α and IL-6 cytokines were significantly higher in patients with active viral infection/coinfection (52.51 ± 15.13 pg/mL, 18.59 ± 3.56 pg/mL, resp)." (PMID 22927850, 2012). "The distribution of BDV-N was similar as described for adult infected rats and indicates a persistent virus infection even in TNF-overexpressing animals." (PMID 22848506, 2012). "CD8+ cytotoxic T cells secreting interferon-gamma (IFN-γ) or/and tumor necrosis factor alpha (TNF-α) are important components in mediating host immunity against viral infections and have been shown to play critical roles in BKV clearance." (PMID 23251224, 2012). "Beginning with a low dose (1 × 106 CFU) of heat killed pneumococcal stimulation after virus infection, MoDCs produced significantly lower amount of TNF-α and IL-6 than that treated with pneumococcus alone." (PMID 21771345, 2011). "The stimuli that trigger activation of these transcription factors include TNFα and IL-1, bacterial products (LPS) or viral infections such as HIV, HCV and HCMV." (PMID 22032643, 2011). "In contrast, infection with the human apathogenic TCRV resulted in a strong up-regulation of several of these cytokines (IL-6, TNF-α and IL-10) in a manner that, for IL-6 and IL-10, was dependent on productive virus infection." (PMID 21572983, 2011).
viral infection (continued). "Phosphorylation of the α subunit of eukaryotic initiation factor 2 (eIF2) through protein kinase R (PKR) is induced by IFN-γ and TNF-α as well as a variety of stress conditions, including viral infection, and has been shown to down-regulate protein synthesis." (PMID 21995976, 2011). "TNFα has been shown to induce inflammation and apoptosis, thereby limiting viral infection, through a wide variety of mechanisms." (PMID 22206025, 2011). "The best characterized example is redistribution of mitochondria to the Golgi-proximal microtubule organizing center in cells exposed to TNFα, oxidative stress or viral infection." (PMID 21858038, 2011). "Over-production of specific inflammatory cytokines, such as the tumor necrosis factor (TNF)-a, interleukin (IL)-1, IL-6 and IL-10, as well as the polymorphonuclear neutrophil CC chemokine (chemokine) IL-8, is the hallmark of viral infection." (PMID 22174866, 2011). "Our in vitro digests utilised immunoproteasomes as they are typically induced within the first day of viral infection by exposure to IFNγ or TNFα." (PMID 21589893, 2011). "Nonetheless, increased levels of IL-10, IFN-γ and TNF-α indicate the presence of fungal, bacterial or viral infection." (PMID 21619669, 2011). "For instance, with a low dose of pneumococcus, the preceding virus infection appeared to be determinative in skewing the MoDC cytokine production towards suppression of TNF-α, IL-6 and IL-10 as stimulated by the bacteria." (PMID 21771345, 2011). "IRF1 is expressed at low levels in unstimulated cells and is activated by many cytokines including type I (IFNα, IFNβ, and others) and II (IFNγ) interferons, tumor necrosis factor-α (TNF-α), retinoic acid, interleukin-1 (IL-1), IL-6, and viral infection." (PMID 22295238, 2011). "The production of these cytokines was further shown to be mechanistically distinct as both IL-6 and IL-10 production were dependent on productive virus infection while TNF-α production was also induced by UV-inactivated particles." (PMID 21572983, 2011). "In particular, secretion of type I IFN is a key step in the innate immune response to viral infection and TNF-α released by DCs can further recruit DC precursors and sustain the antigen presentation." (PMID 21269456, 2011). "In general, IAPs have been shown to protect cells from a wide range of apoptotic triggers including Fas ligation, bax, activated caspases, cytochrome C, TNFα, some chemotherapeutic agents viral infection and radiation." (PMID 20078866, 2010). "Monocytes from RSV-infected infants produced even lower TNF-α levels compared to healthy infants implicating acquired innate immunity suppression frequently observed in acute viral infections, respectively." (PMID 20946625, 2010). "Our current study and former published reports suggest that in vitro responses to viral proteins or peptides are of help to identify risks of viral infection in patients treated with anti-TNF." (PMID 20633267, 2010). "The two groups display similar peak virus recoveries, but, likewise similar to our results, the neonatal calves experienced limited TNF-alpha expression and neutrophil recruitment in response to acute virus infection." (PMID 21078159, 2010). "Together, these results confirm our in vitro data indicating that SP thymocytes are impaired in their ability to produce TNF efficiently when compared to naïve splenic T cells during a viral infection." (PMID 21124839, 2010). "Virus infection in the brain at 4 days p.i. was accompanied by IFNβ and TNFα responses; these antiviral responses waned rapidly by 14 days and there was control of virus replication during this period." (PMID 20019816, 2009). "Enhanced TNF levels were observed as early as 2 days and increased over time to a maximum between days 5 and 10, paralleling viral infection." (PMID 19048100, 2008). "To this end, we infected monocyte-derived pHMs with MV and then measured TNF production in response to the viral infection." (PMID 18617992, 2008).
viral infection (continued). "STAG2, an enhancer of TNF production, and the member of the MAPK pathway, ATF2, a transcription activator of both IFN-β and TNF-α in response to virus infection, were downregulated." (PMID 18796724, 2008). "TNF-α plays a central role in host defence against viral infection." (PMID 39956903, 2025). "The resulting network revealed a highly interconnected core centered around key cytokines—including IL-6, IL-1β, IL-10, TNF-α, IL-18, and GM-CSF—which function as pivotal hubs driving the host inflammatory response and immunopathogenesis in both viral infections." (PMID 41366310, 2025). "Among individuals receiving TNF-α inhibitors, mycobacterium tuberculosis accounts for 12.5–59% of all infections; pneumocystis jirovecii constitutes 20% of all non-viral infections; and the incidence of legionella pneumophila infections is 13–21 times higher compared to the general population." (PMID 40763141, 2025). "The authors suggested that the downregulation of Th1 immune responses from TNF-alpha blockade may have indirectly induced PR by facilitating a viral infection or reactivation." (PMID 39804489, 2025). "The antigen-specific mCD4+ T cells clustered in areas associated with interferon gamma (IFN-γ), tumor necrosis factor (TNF), and interleukin-2 (IL-2) expression, which are the signature cytokines of the type 1 T helper (TH1) cells typically induced during viral infections." (PMID 40124502, 2025). "Pro-inflammatory cytokines (IL-6, TNF-α) are released by neutrophils and macrophages in response to bacterial infections.Interferons and cytotoxic reactions are brought on by viral infections.Immune exhaustion is brought on by persistent illnesses, such as HIV." (PMID 40364844, 2025). "Given that TNFα, LPS and virus infection are canonical factors for activation of NF‐κB pathway, we sought to investigate whether copper could affect these canonical upstream regulators for NF‐κB signaling." (PMID 40999870, 2025). "Also, IL-10 was highly expressed, which has been involved in counteracting the pro-inflammatory effects of TNF-α and IL-6 while mitigating glutamate toxicity, factors responsible of neuropathogenic processes, including viral infections." (PMID 41474758, 2025). "For instance, exposure to cytokine TNFα, challenge with LPS or viral infection leads to a rapid increase in mRNA levels of TNF, chemokine (C-X-C motif) ligand CXCL1, CXCL2, CCL20, IL-6 and IL-1β within 30 min in human HEK293 cells, mouse MLE-12 cells, and mouse lungs." (PMID 39741341, 2025). "In the pathogenesis of viral infections, metabolic responses such as decreased insulin sensitivity, increased hepatic gluconeogenesis, and accelerated lipolysis are involved under the influence of proinflammatory cytokines (e.g., TNF-α, IL-6)." (PMID 41150364, 2025). "From an immunological perspective, vaccines and viral infections act as potent immune stimulants through activation of Toll-like receptors, antigen-presenting cells, and subsequent cytokine cascades, particularly IL-1β, IL-6, and TNF-α." (PMID 41155751, 2025). "TNF-α is a crucial immune player in limiting viral infections." (PMID 40895576, 2025). "These manipulations, which mimic bacterial and viral infections, may promote sleep through shared mechanisms, for example, via proinflammatory cytokines such as tumor necrosis factor and interleukin-1β." (PMID 41370374, 2025). "IL-10 could suppress the production of pro-inflammatory cytokines (e.g., TNF-α, IL-6), thereby limiting inflammation and tissue damage during acute viral infection (e.g., SARS-CoV-2, H1N1, respiratory syncytial virus (RSV))." (PMID 41156600, 2025). "While decreasing and unchanged GBRs produced weak signatures, the increasing GBRs near IL1B-plus-budesonide-induced DEGs yielded a striking inflammatory GO signature that included terms for inflammation, viral infection, and TNFα, IL-17, NOD, and TLR signaling." (PMID 41488369, 2025).